MANBA (mannosidase beta)
Description:
Exoglycosidase that cleaves the single beta-linked mannose residue from the non-reducing end of all N-linked glycoprotein oligosaccharides.
Synonyms: MANB1
Tractability: Small molecule: it belongs to a druggable protein family. Antibody: its Gene Ontology location is reachable by antibodies, with high confidence; UniProt predicts a signal peptide or a membrane-spanning region. PROTAC: ubiquitination databases record sites on it; its protein half-life has been measured; a small molecule that binds it is known.
Target class: Enzyme; Hydrolase
Gene: Protein-coding gene on chromosome 4 (102,630,770 to 102,760,999, reverse strand). Ensembl gene ENSG00000109323.
Subcellular location: Lysosome
Subcellular location (Human Protein Atlas): Vesicles
Pathways (Reactome):
Immune System: Neutrophil degranulation
Metabolism: Lysosomal oligosaccharide catabolism
Gene Ontology:
Molecular function: beta-mannosidase activity; hydrolase activity, hydrolyzing O-glycosyl compounds
Biological process: glycoprotein catabolic process; oligosaccharide catabolic process; protein modification process; carbohydrate metabolic process
Cellular component: azurophil granule membrane; lysosomal lumen; plasma membrane; lysosome
Genetic constraint (gnomAD): Loss-of-function variants: 47 observed, 72.56 expected, observed/expected ratio (o/e) 0.65, 90% interval 0.51 to 0.83. The upper end of that interval is the gene's LOEUF score, 0.83, which puts it in group 3 of 6, group 1 being the genes least tolerant of losing a copy. Missense variants: 802 observed, 806.91 expected, observed/expected ratio (o/e) 0.99, 90% interval 0.94 to 1.05. Synonymous variants: 288 observed, 294.65 expected, observed/expected ratio (o/e) 0.98, 90% interval 0.89 to 1.08.
Gene-disease validity (ClinGen):
ClinGen rates the evidence that MANBA causes each of these diseases.
beta-mannosidosis (autosomal recessive): Definitive. Beta-mannosidosis is a very rare lysosomal storage disease characterized by developmental delay of varying severity and hearing loss, but that can manifest a wide phenotypic heterogeneity.
Homologues: Orthologues: chimpanzee MANBA (99% identical), macaque MANBA (95% identical), dog MANBA (81% identical), pig MANBA (80% identical), rabbit MANBA (78% identical), mouse Manba (76% identical), rat Manba (75% identical), guinea pig MANBA (70% identical), tropical clawed frog manba (59% identical), zebrafish manba (55% identical), Drosophila melanogaster beta-Man (36% identical), Caenorhabditis elegans C33G3.4 (33% identical). Paralogues in human: GUSB (15% identical).
Diseases named in the same sentence as MANBA in open-access papers:
MANBA is named in the same sentence as 38 diseases in open-access papers, as found by Europe PMC text mining. Sharing a sentence is not in itself a finding about the gene and the disease. The quoted sentences say what the papers report.
beta-mannosidosis (4 papers, 2009 to 2023). "Variants in MANBA cause a rare lysosomal storage disorder named beta-mannosidosis whose clinical manifestation includes deafness and mental retardation." (PMID 32847582, 2020). "Since 1986, only 23 patients with beta-mannosidosis and biallelic MANBA variants have been described worldwide." (PMID 32847582, 2020). "A number of mutations in MANBA have been described that cause an extremely rare lysosomal storage disorder called beta-mannosidosis that typically presents with developmental delay and intellectual disability, and increased risk for seizures, infections, and hearing loss." (PMID 32968041, 2020). "We now report on further 10 beta-mannosidosis patients of Roma origin from eight families in the Czech and Slovak Republics with hearing loss, mental retardation and homozygous pathogenic variants in MANBA." (PMID 32847582, 2020). "The MANBA c.2158-2A>G variant in homozygous patients with hearing loss was also found to cause moderate mental retardation, in line with findings in previously reported beta-mannosidosis patients." (PMID 32847582, 2020). "The present analysis of the c.1922G>A MANBA mutation underlines the lack of genotype-phenotype correlation in beta-mannosidosis." (PMID 19728872, 2009). "The loss of enzymatic activities of other well studied family members, including lysosomal alpha-mannosidase (MAN2B1) and mannosidase beta (MANBA), resulted in alpha- and beta- mannosidosis." (PMID 35637269, 2023).
lysosomal storage disorder (4 papers, 2009 to 2022). "β-Mannosidosis (OMIM 248510) is a rare inborn lysosomal storage disorder caused by the deficient activity of β-mannosidase, an enzyme encoded by a single gene (MANBA) located on chromosome 4q22-25." (PMID 19728872, 2009). "Next, mutations in MANBA, which encodes β-mannosidase, have been found to cause β-mannosidosis [MIM: 248510], a lysosomal storage disorder most commonly characterized by mental retardation, hearing loss, and frequent infections." (PMID 35996156, 2022).
Intellectual disability (3 papers, 2020 to 2023). "Interestingly, the loss of function of three of the six human-biased glycan degradation genes (MANBA, MAN2B2, and MAN2B1) is associated with intellectual disability." (PMID 36658652, 2023).
schizophrenia (3 papers, 2016 to 2021). A major psychotic disorder characterized by abnormalities in the perception or expression of reality. "Previous studies identified MANBA as a gene that is associated with schizophrenia and nicotine dependence, as well as antipsychotic response." (PMID 35052433, 2021). "Among the FG loci with sex-homogeneous effects, variants at the MANBA/UBE2D3, NFATC3, and IGF1R provided insights into pathways involved in glucose homeostasis and relationships with other complex phenotypes, including neurodegeneration, schizophrenia, and cancer." (PMID 33402679, 2021).
autoimmune disease (2 papers, 2021 to 2022). A disorder resulting from loss of function or tissue destruction of an organ or multiple organs, arising from humoral or cellular immune responses of the individual to their own tissue constituents. "A recent study in primary biliary cholangitis, another autoimmune disease, confirmed the existence of two different LD blocks in this region: one regulating NFĸB and represented by rs17032850, and another including MANBA and represented by rs227361." (PMID 35897697, 2022). "Interestingly, the lead SNP at the MANBA/UBE2D3 locus, rs223486, is an intergenic variant located in a region (±500 kb) that harbors several other genes (CISD2, NFKB1, SLC9B1/2, BDH2 and CENPE) with reported inflammatory and autoimmune disease associations." (PMID 33402679, 2021).
hearing loss (2 papers, 2020). "Among the 250 Roma patients with an as yet unclarified cause of hereditary hearing loss, nine patients from seven families were found to be homozygous for the pathogenic variant c.2158-2A>G in the MANBA gene." (PMID 32847582, 2020). "Interestingly, one additional homozygote for MANBA c.2158-2A>G was also detected in a group of 59 Roma patients with an already clarified cause of hearing loss, namely in a homozygote for GJB2 c.71G>A (p.W24*) variant." (PMID 32847582, 2020). "If we try to trace the origin of the MANBA variant, we have to consider the following facts: our findings show the variant c.2158-2A>G to be an important cause of hearing loss in the Czech and Slovak Roma, but not in non-Roma European populations." (PMID 32847582, 2020).
migraine (2 papers, 2020 to 2023). "In addition, genomic regions containing the MANBA gene are associated with migraine and small vessel disease." (PMID 36808568, 2023). "We also identified the MANBA locus as a significant pleiotropic region (chr4: 103221459-105304491) in the GWAS-PW analyses for migraine and FG, headache and FG, and headache and glucose." (PMID 36808568, 2023). "TWAS genes with independent effects shared by subtypes of migraine and BP were consistent with findings for overall migraine at ITGB5, while identifying additional associations at HMOX2 for MA and BP, and HVCN1 and MANBA for MO and BP." (PMID 32632093, 2020). "A study of the MANBA expression in brain tissues suggests that the cerebellar cortex, medulla, and pons are the primary sites where it is expressed, in line with the idea that the cerebellar cortex plays a role in migraine pathophysiology." (PMID 36808568, 2023). "However, further research is required to confirm and understand the genetic basis and involvement of MANBA in the onset and progression of diseases like migraine and glycemic traits." (PMID 36808568, 2023). "Interestingly, a novel locus mapped to the MANBA gene was common across the migraine, headache, and glycemic traits." (PMID 36808568, 2023).
primary biliary cholangitis (2 papers, 2022 to 2023). Primary biliary cholangitis (PBC) is a chronic and slowly progressive cholestatic liver disease of autoimmune etiology characterized by injury of the intrahepatic bile ducts that may eventually lead to liver failure. "The MANBA/NFKB1 region was identified in previous studies as a disease susceptibility locus for primary biliary cholangitis (PBC) and a recent study found a decreased level of IgG galactosylation in PBC patients." (PMID 38149987, 2023).
alcohol dependence (1 paper, 2012). Physical and psychological dependence on alcohol. "Four genes, MAPK1 (marijuana dependence in black women), MANBA (alcohol dependence in white men), HAAO (cocaine dependence in white women), and IFNG (opiates dependence in white women), met the threshold by the gene-based method only." (PMID 23365539, 2012).
attention deficit-hyperactivity disorder (1 paper, 2022). A disorder characterized by a marked pattern of inattention and/or hyperactivity-impulsivity that is inconsistent with developmental level and clearly interferes with functioning in at least two settings (e.g. at home and at school). "In addition, genetic variants in MANBA have also been identified in infantile nystagmus and attention deficit hyperactivity disorder." (PMID 35897697, 2022). "In this regard, a recent study on attention deficit hyperactivity disorder showed that rs1054037, a perfect proxy of rs7665090, upregulates MANBA expression by disrupting the binding site of hsa-mir-5591-3p." (PMID 35897697, 2022).
breast carcinoma (1 paper, 2022). "Still, TAGL and MANBA were selected in all butbreast cancer models, and GTR1 and LEG10 in all but the pan-cancerand breast cancer models." (PMID 35605973, 2022).
cerebellar ataxia (1 paper, 2017). A neurological syndrome characterized by clumsy and uncoordinated movement of the limbs, trunk, and cranial muscles. "The very rare mutations in MANBA results in β-mannosidosis with a severe neurological disorder that can include mental retardation, cerebellar ataxia along with visual and hearing deficits." (PMID 28993790, 2017).
colorectal cancer (1 paper, 2023). A primary or metastatic malignant neoplasm that affects the colon or rectum. "In some studies, the role of MANBA in cancer has been reported, such as being involved in the occurrence and metastasis of colorectal cancer and human esophageal squamous cell carcinoma." (PMID 38274828, 2023).
COVID-19 (1 paper, 2025). A disease caused by infection with severe acute respiratory syndrome coronavirus 2. "Lysosomal-associated membrane proteins (LAMP) and lysosomal hydrolases, mannosidases (MANBA), glucosylceramidase beta 1 (GBA), and Asp-glucosaminidases (AGA) were upregulated in COVID-19(+) cardiac tissues." (PMID 39988192, 2025).
glioblastoma (1 paper, 2023). The most malignant astrocytic tumor (WHO grade IV). "Considering the involvement of MANBA in glioblastoma, we opted to study the effects of MANBA knockdown on two glioblastoma cell lines, namely U87 and LN229." (PMID 38274828, 2023). "Accordingly, we proceeded with further experiments to validate the role of MANBA in fostering the proliferation, invasion, and metastasis of glioblastoma cells." (PMID 38274828, 2023).
leukemia (1 paper, 2023). A malignant (clonal) hematologic disorder, involving hematopoietic stem cells and characterized by the presence of primitive or atypical myeloid or lymphoid cells in the bone marrow and the blood. "We identified recurrently affected genes by SVs, such as FOCAD/HACD4, MANBA, and SFMBT2 that were validated by long-read sequencing and/or RNA-seq in at least 1 leukemia." (PMID 37469802, 2023).
mucopolysaccharidoses (1 paper, 2023). "Beyond sphingolipid/ceramide metabolism, our screen also identifies many fly homologs of genes causing human mucopolysaccharidoses (e.g., GLB1, IDS, IDUA, MAN2B1, MANBA)." (PMID 37200393, 2023). "In an independent longitudinal proteomics dataset we replicated αSyn-induced increases among 6 of these proteins, including Npc1a and several proteins homologous to human LSD gene products causing mucopolysaccharidoses: GLB1/Ect3, MAN2B1/LManII, and MANBA/Beta-Man." (PMID 37200393, 2023).
multiple sclerosis (1 paper, 2022). A progressive autoimmune disorder affecting the central nervous system resulting in demyelination. "The single nucleotide polymorphism located in the 3′UTR of MANBA, rs7665090, was found to be associated with multiple sclerosis (MS) susceptibility." (PMID 35897697, 2022).
Oral leukoplakia (1 paper, 2026). A thickened white patch on the oral mucosa that cannot be rubbed off. "Fine-mapping revealed 14 coding variants, such as a missense variant in USP31 for caries and in MANBA for oral leukoplakia, and a stop-gained variant in GPNMB for temporomandibular disorders." (PMID 42310951, 2026).
rheumatoid arthritis (1 paper, 2021). A chronic, systemic autoimmune disorder characterized by inflammation in the synovial membranes and articular surfaces. "The expression levels of the two genes that showed significant association with ADHD (MANBA and LEPRE1) were also significantly associated with body mass index, rheumatoid arthritis and SCZ." (PMID 31628418, 2021).
kidney disease (3 papers, 2021 to 2025). "Although many genetic variants associated with CKD have been identified, correlation analysis focusing on MANBA gene variants that directly affect kidney diseases are rare." (PMID 34070965, 2021). "While at the moment we do not know putative mechanisms that could explain the link between MANBA, G0 and cardiovascular or renal diseases, these intriguing associations warrant future studies." (PMID 38149987, 2023). "Thus, they performed eQTL analysis of the renal tubules and glomeruli and identified genes that may cause kidney disease, including the MANBA gene." (PMID 34070965, 2021). "Among them, MANBA, PGAP3, and CASP9 were confirmed to have functional roles in kidney disease development in previous animal studies." (PMID 34070965, 2021).
cancer (2 papers, 2022 to 2023). A tumor composed of atypical neoplastic, often pleomorphic cells that invade other tissues. "These candidates have rather decreasing (HV404, XPP1, MANBA, TENX)or increasing (LEG1, C4BPB) trends in a cancer agnostic manner, withthe exception of GTR1, which strongly increases in the late-stagebreast cancer while decreasing in the other types." (PMID 35605973, 2022).
neurological disease (2 papers, 2009 to 2017). "Correlations between MANBA mutations, residual activity of β-mannosidase and the severity of the ensuing neurological disorder are discussed." (PMID 19728872, 2009). "This is the first report of a MANBA missense mutation present at the homozygous state and which retains a residual activity while being associated with a severe neurological disease." (PMID 19728872, 2009).
tumor (2 papers, 2022 to 2023). "Remarkably, MANBA appears to participate in the modulation of neuroimmune functionality by exerting inhibitory effects on M1-polarized macrophages, thereby fostering tumor progression." (PMID 38274828, 2023). "Based on this, we postulate that MANBA may inhibit the generation, transformation, and activity of M1 macrophages, thereby promoting tumor growth and adversely affecting the prognosis of GBM patients." (PMID 38274828, 2023). "Moreover, transwell assays confirmed the inhibitory effects of MANBA knockdown on tumor cell migration." (PMID 38274828, 2023). "LGALS1, B4GALT6, and GALNT11 were upregulated and MGAT5, MAN1A1, MANBA, LUM, GALNT1 and 7, HAPLN3, and ST6GALNAC5 were downregulated in Fra-2 cl 1 select primary tumours, while MGAT4A was upregulated." (PMID 34693476, 2022). "This leads us to speculate that the tumor microenvironment in GBM may provide a conducive milieu for tumor growth, with MANBA possibly playing a role therein." (PMID 38274828, 2023).
MANBA also shares sentences with these, for which no sentence is quoted: chronic kidney disease (2 papers); 3-methylglutaconic aciduria type 1 (1); cardiovascular disease (1); cocaine dependence (1); deafness (1); developmental delay (1); esophageal squamous cell carcinoma (1); Headache (1); marijuana dependence (1); nephropathies (1); nephrotic syndrome (1); nicotine dependence (1); opiate dependence (1); ulcerative colitis (1).